UCP1 (uncoupling protein 1)
Diseases named in the same sentence as UCP1 in open-access papers (continued):
Sharing a sentence is not in itself a finding about the gene and the disease.
tumor (continued). "The results showed that UCP1 was significantly up-regulated in 11 tumor types and down-regulated in 7 cancers, including BC." (PMID 35874806, 2022). "Expression levels of UCP1, a key thermogenic protein, were accordingly increased in tumour-bearing mice as observed in tumour-free mice." (PMID 35922508, 2022). "Increased UCP-1 protein amount of LLC tumor-bearing mice was verified by Western blotting analyses and revealed 4- and 3.5-fold higher UCP-1 protein abundance in iWAT and aWAT, respectively." (PMID 35210363, 2022). "UCP1 was associated with enhanced FAO and glutamine metabolism, while UCP2 with enhanced anti-tumor immunity." (PMID 35874806, 2022). "The removal of BAT and feeding on a high-glucose diet under cold exposure restore tumour growth, and genetic deletion of Ucp1—the key mediator for BAT-thermogenesis—ablates the cold-triggered anticancer effect." (PMID 35922508, 2022). "The expression of UCP1 was crucially correlated with immune infiltration, tumor invasion, epithelial-mesenchymal transition (EMT), metastasis and DNA repair." (PMID 35090503, 2022). "In iWAT and aWAT of C26 tumor-bearing mice, UCP-1 protein levels were 2.9- and 3.2-fold higher, respectively, than in control mice." (PMID 35210363, 2022). "UCP1-dependent lipid browning procedure elicits a catabolic state, referred to as “tumor slimming” and inhibits tumor progression." (PMID 35874806, 2022). "In this study, a selective enrichment of BAT-selective genes was observed in the tumor as well as the host cells, and a depletion of UCP1 and the Myf5-positive population resulted in a significantly reduced tumor size." (PMID 34831253, 2021). "Tumor implantation induced increases in UCP-1 expression in iWAT and BAT in both genotypes and these increases were more pronounced in Ghsr−/− than in Ghsr+/+." (PMID 32934774, 2020). "Higher levels of uncoupling protein-1 (UCP-1) were found in the tumor environment upon curcumin administration, indicative of brown adipose fat (BAT) formation." (PMID 33182828, 2020). "In BAT, the positively stained UCP-1 area increased with tumor implantation from 22% to 59% in Ghsr+/+ and from 35% to 70% in Ghsr−/− mice (genotype effect: p = 0.005)." (PMID 32934774, 2020). "In a study using a mouse xenograft model, UCP1 expression was essential for tumorigenic ability, and its expression decreased in accordance with tumor progression." (PMID 32647572, 2020). "Here, it is demonstrated that phospholipase C‐like 1/uncoupling protein 1 (PLCL1)/(UCP1)‐mediated lipid browning promotes tumor cell “slimming” and represses tumor progression." (PMID 31131187, 2019). "BAT from Pan02 tumor-bearing mice displayed smaller adipocytes containing less and/or smaller lipid droplets and showed a moderate reduction in UCP1 protein levels." (PMID 31073508, 2019). "Collectively, the data indicate that lipid browning mediated by PLCL1/UCP1 promotes tumor cell “slimming” and consumes abnormal lipid accumulation, which represses the progression of ccRCC." (PMID 31131187, 2019). "IHC (immunohistochemistry) staining was conducted to evaluate the expression of PLCL1 and UCP1 in a xenograft tumor, and the results were consistent with the cell results." (PMID 31131187, 2019). "Mechanistic and functional research showed that PLCL1 promoted this process and repressed tumor progression through lipid browning mediated by UCP1." (PMID 31131187, 2019). "We conclude that PLCL1 repressed the progression of ccRCC and promoted tumor cell “slimming” mainly through UCP1‐mediated lipid browning." (PMID 31131187, 2019). "An inclination to the correlation with better tumor differentiation was seen for UCP1 and CD68 protein expression in patients with MHO and with worse (high grade) differentiation—for CD68 expression in the group with SO." (PMID 27853670, 2016). "It has also been found that in pancreatic cells, expression of UCP1 increased oxygen consumption and decreased tumor growth." (PMID 25291184, 2014).
tumor (continued). "Conversely, expression of the mitochondrial uncoupling protein 1 (UCP1) increased oxygen consumption and decreased tumor growth." (PMID 19753307, 2009). "Induction of UCP-1, -2 and -3 expression by tumour-derived LMF probably provides a mechanism for excessive lipid disposal, which in turn facilitates the fat catabolic cascade in malignancy." (PMID 11870545, 2002). "Conversely, depletion of UCP1-positive cells markedly suppresses tumour development." (PMID 41498391, 2026). "Importantly, BAT removal or feeding mice a high-glucose diet restored tumor growth under cold conditions, while genetic deletion of UCP1 abolished the anti-cancer effects of BAT thermogenesis." (PMID 41551882, 2026). "A relatively lower expression of UCP-1 was observed in preprostate fat distant from the tumor." (PMID 40437336, 2025). "Importantly, these anticancer effects are abolished in Ucp1-deficient mice, indicating that mitochondrial uncoupling is essential for BAT-mediated tumor suppression." (PMID 40983641, 2025). "To examine whether UCP1-modulated adipose organoids can prevent glucose uptake in the co-transplanted xenograft tumor, we measure glucose levels in both the adipose organoids and co-implanted MCF-7 tumor." (PMID 39905264, 2025). "Furthermore, PLCL1 decreased lipid accumulation through UCP1-mediated lipid browning and facilitated tumor apoptosis by activating p38 phosphorylation." (PMID 40083699, 2025). "More importantly, UCP1 ablation largely ameliorated LLC tumour-induced cachectic manifestations in the UCP1 knockout mice relative to their wild-type (WT) littermates with similar tumour burden, suggesting that upregulation of UCP1 is essentially involved in the pathogenesis of cancer cachexia." (PMID 38499763, 2024). "However, the thermogenic effectors were indeed increased in all tumor-bearing mice at both the mRNA and protein levels, for example, thermogenic factor UCP-1 in the white fat depots." (PMID 39273055, 2024). "Furthermore, tumor glucose metabolism-related gene expressions were largely restored in Ucp1−/− mice." (PMID 37993438, 2023). "Whether activating these UCP1-independent NST mechanisms inhibits tumor growth requires further investigation." (PMID 37993438, 2023). "Genetic deletion of Ucp1 in mice or surgical removal of adipose depots abrogated tumor suppression." (PMID 37993438, 2023). "Moreover, UCP1 expression correlated to several immune cell markers and regulated tumorigenesis, such as tumor invasion, EMT, metastasis and DNA repair." (PMID 35090503, 2022). "Similarly, deletion of Ucp1 elevated tumour cell proliferation and hypoxia to the thermoneutral levels." (PMID 35922508, 2022). "Results also suggested that a UCP-1 independent cascade could also regulate adipocyte homeostasis and influence tumor-induced WAT wasting." (PMID 36499637, 2022). "Consistently, it was reported that Ucp1 expression remained unchanged in scWAT, and Ucp1 mRNA expression rather decreased coincidently with Pparg mRNA expression in brown adipose tissue from Pan02-tumor-bearing mice." (PMID 36230682, 2022). "Simultaneously, lymph node metastasis promotes factor, vascular endothelial growth factor (VEGF) and matrix metalloproteinase 1 (MMP1), one key enzyme activating extracellular matrix proteolysis during tumor metastasis, have been down-regulated while overexpressing UCP1." (PMID 35541900, 2022). "Based on cancer single cell sequencing data, tumor functional status analyses suggest that UCP1 may down regulate invasion, EMT, metastasis, DNA repair and angiogenesis." (PMID 35090503, 2022). "Future research needs to consider the role of UCP1 expression in tumor thermogenesis." (PMID 35874806, 2022). "The UCP1-dependent tumour suppression by cold may potentially reflect the mitochondrion-dependent suppression by BAT." (PMID 35922508, 2022).
tumor (continued). "Genetic deletion of Ucp1 abolished the tumour-suppressive effect of cold exposure." (PMID 35922508, 2022). "BAT removal and genetic deletion of Ucp1 restored the tumour growth rate under cold exposure." (PMID 35922508, 2022). "While it is not clear if cachexia in human cancer patients involves UCP1-mediated uncoupled thermogenesis activation, AT lipolysis in cancer is clearly linked with tumor aggressiveness." (PMID 35835372, 2022). "However, UCP1 reportedly can inhibit tumor progression by initiating autophagy and lipid browning programs, along with snail-mediated repression of fructose-bisphosphatase 1 (FBP1)." (PMID 35874806, 2022). "In addition, melatonin/PGC1A/UCP1 promotes tumor slimming and restrains tumor progression by initiating autophagy and lipid browning." (PMID 33381557, 2020). "Restoration of PLCL1 expression in ccRCC cells repressed tumor progression, reduced abnormal lipid accumulation, and caused tumor cell “slimming” through UCP1-mediated lipid browning, which consumes lipids without producing ATP energy." (PMID 32762776, 2020). "UCP1 is highly expressed in hibernoma, a tumour containing abundant BAT cells." (PMID 31114671, 2019). "We have also determined whether tumour markers other than UCP1 can be used to distinguish hibernoma from other adipose/non-adipose soft tissue tumours." (PMID 31114671, 2019). "Likewise, our results demonstrated that adipocytes co-cultivated with tumor cells exhibited increased UCP1 and monocarboxylate transporter 4 (MCT4) levels and reduced Cav-1 expression compared with single cultivation." (PMID 31500658, 2019). "Conversely, the activation of UCP1+ cells significantly decreases tumor development." (PMID 31500658, 2019). "Importantly, histological analysis of the adipose tissues showed significant morphologic alterations and decreased expression of UCP1 in Pan02 tumor-bearing mice." (PMID 31073508, 2019). "From a lipid metabolism standpoint, UCP1‐overexpressing cells also showed a significant decrease in lipid accumulation accompanied by lipid droplet transformation into small pieces and a decrease in tumor cell volume." (PMID 31131187, 2019). "More UCP1 positive beige adipocytes were observed in tumor implanted mice." (PMID 29245988, 2017). "The UCP1 content in iWAT was increased due to both tumor implantation and alcohol consumption." (PMID 29245988, 2017). "Consequently, alcohol increased PR/SET Domain 16 (PRDM16) and UCP1 protein contents in iWAT of tumor mice." (PMID 29245988, 2017). "To further test whether nutrient competition is contributory to the ability of UCP1-CRISPRa-treated adipose organoids to suppress tumor growth, we performed similar MCF-7 xenograft experiments with mice fed with either standard chow, a high-fat diet (HFD) or 15% glucose containing water." (PMID 39905264, 2025). "Notably, BA activation consumes glucose through UCP1-mediated thermogenesis, which may restrict glucose availability in the tumor microenvironment." (PMID 41595468, 2025). "In addition to Ucp1 induction, white adipocytes in vehicle-treated OSRC-2 tumor-bearing mice exhibited the hallmark switch from unilocular lipid-storing white adipocytes to multilocular thermogenic brown/beige adipocytes, a process that was blocked upon PT2399 treatment." (PMID 40964365, 2025). "Studies have found that peroxisome proliferative activated receptor gamma coactivator 1 alpha (PGC1α) and phospholipase C like 1 (PLCL1) mediated cellular browning by regulating uncoupling protein 1 (UCP1) level could promote tumor “slimming” and inhibit tumor progression." (PMID 37025584, 2023). "Similarly, Ucp1−/− restored tumor cell proliferation and hypoxia." (PMID 37993438, 2023). "Similarly, genetic deletion of Ucp1 also ablates cold-induced tumour suppression." (PMID 35922508, 2022).
tumor (continued). "In addition, high expression of UCP1 was detected specifically in the resident adipose tissue and in adipocytes that were co-cultivated with tumor cells, demonstrating that CAAs may have a similar mechanism as that of CAFs." (PMID 31500658, 2019). "In breast cancer models, tumour-derived adrenomedullin (ADM), a hypoxia-inducible peptide, drives UCP1 expression in adjacent adipocytes through paracrine signalling." (PMID 40943351, 2025). "In vitro co-culture models incorporating tumour cells, adipocytes, and macrophages will be essential for dissecting the interplay between statin pharmacodynamics, PAR-2 activity, and UCP1 expression." (PMID 40943351, 2025). "It acts as a tumor suppressor in certain cancers through pathways like WNT/β‐catenin/PDK1, PGC1A/ERRA, and Melatonin/PGC1A/UCP1, regulating metabolism, signaling, and autophagy." (PMID 40119647, 2025). "The varying signal intensities of UCP-1 in immunohistochemistry revealed the distribution of BAT and WAT within the periprostatic fat near the tumor region, correlating with the higher water-to-fat ratio observed in mpMRI imaging." (PMID 40437336, 2025). "Taken together, these results show that UCP1-CRISPRa-modulated human adipose organoids significantly reduce glycolysis and FAO, reduce hypoxia and inhibit tumor growth for four different cancer types in vivo." (PMID 39905264, 2025). "Studies investigating the expression and function of UCP1 and its homologs (UCP2 and UCP3) in various tumor types have yielded heterogeneous results." (PMID 40983641, 2025). "Through verification and functional experiments on WAT from tumour-bearing mice and cell lines, we demonstrated that the formation of the GRP75–ANT2–UCP1 complex promoted the stability of UCP1 in GRP75-triggered WAT browning." (PMID 39327432, 2024). "Mechanistically, tumor exosomal IL-8 was demonstrated to induce reprogramming of energy metabolism in CD8 + T cells through overactivating PPARα and uncoupling protein 1 (UCP1), thereby resulting in exhaustion of CD8+ T cells though enhanced starvation." (PMID 38802766, 2024). "COL18A1-AS1/KLF12 positively regulated uncoupling protein 1 (UCP1)–mediated lipid browning, which promotes tumor cell “slimming” and inhibits tumor progression." (PMID 35787628, 2022). "In tumour-sided PRAT matched with SCAT samples, UCP1 expression was 27-fold upregulated (P = 0.026), whereas DIO2 and PRDM16 were downregulated (P = 0.048 and P > 0.05) in PRAT." (PMID 36402906, 2022). "Two typical lipolysis markers, PGC1α and UCP1, were also up-regulated in the adipose tissues of LLC and C26-tumor mice groups, respectively." (PMID 36581870, 2022). "We first analyzed the expression of UCP1 and UCP2 between normal and tumor samples from 34 cancer specimens in TCGA." (PMID 35874806, 2022). "As UCP1 is the crucial mitochondrial protein responsible for NST in adipose tissues, we used Ucp1−/− mice in our tumour experiments." (PMID 35922508, 2022). "UCP1, UCP2, UCP3 and UCP5 expression levels correlated with a favorable prognosis and tumor progression." (PMID 35090503, 2022). "Reduced β-adrenergic activation prevented phosphorylation and activation of HSL and the up-regulation of UCP-1 protein levels in iWAT and aWAT depots of LLC-bearing DBHΔper mice compared with LLC tumor-bearing WT mice." (PMID 35210363, 2022). "To evaluate browning of perirenal AT, we measured mRNA levels of Prdm16, TBX1, Ucp1 and PGC1 alpha in AT from normal and tumor kidney." (PMID 35606546, 2022). "Another mechanism contributes to a poor prognosis in ovarian cancer is that of increased UCP-1 activity in brown adipose tissue of PRAT, resulting in increased resting energy expenditure which results in tumor cachexia." (PMID 33800984, 2021). "In this experiment, browning marker UCP1 expression was increased, and AMPK was inactivated in the tumor group." (PMID 33086629, 2020). "Thus, the lipid browning activated by UCP1 could also promote tumor cell “slimming” in ccRCC." (PMID 31131187, 2019).
tumor (continued). "UCP1-dependent proton leak is indispensable for thermogenesis and improves systemic glucose utilization, and recent studies demonstrate that BAT thermogenesis can suppress tumor growth by competing with cancer cells for glucose." (PMID 41551882, 2026). "Excessive ROS production by T15 treatment activates different counter mechanisms trying to partially protect the tumor cells against oxidative stress, such as the higher expression of NOX1 on MCF7 cells; PARK7, PRDX1 and PRDX3 on MDA-MB231 cells; and UCP1 elevation in PANC1 cells." (PMID 41011284, 2025). "These distinctions among UCP isoforms suggest that uncoupling OXPHOS could, under certain conditions, promote tumor progression through mechanisms distinct from UCP1-mediated glucose competition observed in BAT." (PMID 40983641, 2025). "UCP1, UCP3, SLC25A27, and SLC25A14 showed significantly lower expression in most tumor tissues." (PMID 41403699, 2025). "These consistent expression patterns suggest that UCP2 may function as an oncogene in diverse cancer contexts, while UCP1, UCP3, SLC25A27, and SLC25A14 are potentially involved in tumor-suppressive mechanisms." (PMID 41403699, 2025). "While mitochondrial uncoupling through UCP1 in BAT appears to exert anticancer effects, early evidence suggests a more complex and context-dependent relationship between mitochondrial proton leak and tumor biology." (PMID 40983641, 2025). "As UCP1 is highly upregulated in adipocytes of activated BAT and browning WAT, we concluded that the β3-AR agonist significantly induced an increase in UCP1 expression levels in PAT but did not affect tumor tissue in our study." (PMID 40500705, 2025). "MAC16 tumor-bearing mice showed the overexpression of UCP-1 in BAT, which may be to counter the effect of the hypothermia generated by tumor-derived factors." (PMID 36900198, 2023). "Consistent with a decreased β-adrenergic tone, UCP-1 protein content was reduced in iWAT and aWAT depots of LLC tumor-bearing IL-4ra-KO mice compared with WT depots, corroborating the conclusion that IL-4ra–dependent IL-4 activation of macrophages regulates sympathetic activity and WAT browning." (PMID 35210363, 2022). "Further studies show that PLCL1 promotes tumor cell “slimming” and represses tumor progression through UCP1‐mediated lipid browning, which consumes lipids without producing ATP energy." (PMID 31131187, 2019). "Absence of UCP1 staining in most adipose tumours would also indicate that ‘browning’ of WAT to form beige/brite cells is not seen to any great extent." (PMID 31114671, 2019). "Collectively, we suggest a model in which PLCL1 promotes tumor cell “slimming” by increasing the level of UCP1, allowing cells to consume lipids without producing ATP to repress the progression of ccRCC." (PMID 31131187, 2019). "WAT is the predominant form of adipose tissue present in humans after infancy so it is perhaps not surprising that most adipose tumours are composed of cells containing (UCP1-negative) WAT cells." (PMID 31114671, 2019). "Histological analysis of inguinal WAT revealed the presence of smaller adipocytes with big nuclei and multilocular cytoplasm in Pan02 tumor-bearing mice, however, without changes of UCP1 protein levels." (PMID 31073508, 2019). "This hypothesis is supported by our recent findings of increased expression of UCP-1 in BAT, and of UCP-2 and -3 in skeletal muscle in mice bearing the MAC16-tumour, which produces LMF." (PMID 11870545, 2002). "In brown adipose tissue (BAT), proton leak via uncoupling protein 1 (UCP1) is essential for thermogenesis and has been shown to improve systemic glucose homeostasis, and recent studies indicate that BAT activation can also suppress tumor growth by competing with cancer cells for glucose." (PMID 40983641, 2025).